FGFR1 (fibroblast growth factor receptor 1)
Diseases named in the same sentence as FGFR1 in open-access papers (continued):
Sharing a sentence is not in itself a finding about the gene and the disease.
tumor (continued). "Additionally, FGFR1 signaling can recruit immunosuppressive cells, such as regulatory T cells (Tregs) and myeloid-derived suppressor cells (MDSCs), further promoting an immune-permissive environment that protects the tumor from immune attack." (PMID 40547805, 2025). "Consequently, its fusion with FGFR1 may influence immune responses, as well as the proliferation, migration, and survival of tumor cells." (PMID 40242904, 2025). "Finally, FGFR1 overexpression is also critical in tumor pathogenesis." (PMID 40547805, 2025). "Interestingly, FGFR1 signaling in DU 145 cells with the KLF5KR mutant was more sensitive to FGF9, implying that an endogenous pathway in the tumor cells could be involved in the activation of FGFR1 signaling." (PMID 38781024, 2024). "Whole exome sequencing results revealed that such EV-DNA carried tumor-specific genetic mutations, including those occurring on known oncogenes and tumor suppressor genes in neuroblastoma (ALK, CHD5, SHANK2, PHOX2B, TERT, FGFR1, and BRAF), and represented the entire exome." (PMID 39402599, 2024). "Prolonged FGFR1 knockdown may trigger compensatory mechanisms in tumor cells." (PMID 37496658, 2023). "Hence, FGFR1 is functionally relevant for tumor invasion in GBM." (PMID 37579831, 2023). "No clear association between FGFR1 expression in tumor-adjacent or tumor tissue and MBD was found." (PMID 37546410, 2023). "Sulfatinib is a small molecule tyrosine kinase inhibitor that targets tumor angiogenesis and immune modulation, inhibiting vascular endothelial growth factor receptors (VEGFRs) 1, 2, and 3, the fibroblast growth factor receptor type 1 (FGFR1), and colony-stimulating factor 1 receptor (CSF-1R)." (PMID 35897702, 2022). "Diverse treatment outcomes were observed in Sq-NSCLCs with other FGFR variants: SD (4.1 months PFS and 20% tumor shrinkage) was reported in one patient (6.6%) with simultaneous FGFR1 missense variants: D93Y and H841Y, whereas no response was reported in a patient (1/27, 1.4%) with FGFR3 fusion." (PMID 35402233, 2022). "Moreover, lenvatinib, an FDA recently approved multi-kinase inhibitor targeting both VEGFR2 and FGFR1, effectively inhibits the tumor vasculature, and exhibited robust anti-tumor effects in NPC-bearing nude mice and humanized mice compared with an agent equivalent to bevacizumab." (PMID 35985991, 2022). "Importantly, our pilot xenograft experiments showed the trend that FGFR1 knockdown could impair tumor growth of sorafenib-resistant HCC cells in the presence of DJ-1 treatment." (PMID 35770048, 2022). "Interestingly, FGFR1 phosphorylation was increased in the tumor tissues after TAE684 treatment, suggesting that the FGFR pathway might compensate for inhibition of ALK signaling." (PMID 35326668, 2022). "However, without estrogen signaling, it is attractive to speculate with the concept that tumor progression may be driven by other signaling factors such as fibroblast growth factor receptor-1 (FGFR-1), insulin growth factor 1 (IGF-1), or Ob-R." (PMID 34210055, 2021). "However, residual tumor cells survived from cabozantinib treatment due to vascular heterogeneity represents a mechanism of cabozantinib resistance, and the initiation of the expression of FGFR1 in tumor cells is another potential mechanism of acquired resistance to cabozantinib." (PMID 34722310, 2021). "We performed DNA methylation analysis of the encoding genes FGFR1, FGFR2, FGFR3, FGFR4, FGF1-14, FGF16-23, and CCND1 at single CpG site resolution (840 CpG sites) employing The Cancer Genome Research Atlas (TCGA) HNSCC cohort comprising N = 530 tumor tissue and N = 50 normal adjacent tissue samples." (PMID 34933671, 2021). "In the case of FGFR1 driven neoplasms, mechanisms of resistance that have been suggested in animal studies can be monitored during the course of standard ant-FGFR1 treatment to possibly detect emergence of resistant clones, although it cannot be excluded that novel mechanisms may also arise." (PMID 34734169, 2021).
tumor (continued). "Importantly, in support of our hypothesis, analysis of FGFR1 and FGFR4 protein expression of the patient tumor showed co-overexpression of FGFR1 (IHC score 120) and FGFR4 (IHC score 60)." (PMID 33092134, 2020). "Hence, we hypothesized that miR-198 exerts its tumor-suppressive effect in part through the regulation of FGFR1, which is a putative oncogene." (PMID 31138759, 2019). "This may be indicative of a role of activated FGFR1 and tumor progression." (PMID 30931252, 2019). "Notably, FGFR1, known as fibroblast growth factor receptor 1, has been discovered that its copy number amplification is strikingly correlated with FGFR1 gene upregulation and FGFR1 protein upregulation in tumor samples." (PMID 31706287, 2019). "Furthermore, in SW620, administration of axitinib led to a significant tumor growth inhibition, which might be attributed to its relatively high expression of axitinib targets FGFR1 and TNIK." (PMID 31783534, 2019). "Furthermore, combined inhibition of FGFR1 and CDK4/6 in CAMA1 cell line abolished anti-estrogen resistance suggesting that an interaction between FGFR1 and cyclin D1 might drive estrogen-independent proliferation in co-amplified tumours." (PMID 31142340, 2019). "Furthermore, FGFR1 silencing elicited a similar tumor-suppressive effect as miR-198 overexpression." (PMID 31138759, 2019). "Finally, among 391 patients in MONALEESA-2 with tumor gene expression data, those with higher FGFR1 mRNA expression levels have so far exhibited a statistically significant shorter PFS than those with lower FGFR1 mRNA expression levels, consistent with and supportive of the ctDNA NGS finding." (PMID 30914635, 2019). "Recent studies have revealed that the ectopic FGFR1 signaling pathway contributes to PCa progression via multiple mechanisms, including promoting tumor angiogenesis, reprogramming cancer cell metabolism, and potentiating inflammation in the tumor microenvironment." (PMID 30761180, 2019). "However, it was confirmed that miR-214-3p acted as a tumor suppressor by targeting FGFR1." (PMID 31492847, 2019). "Moreover, at CNA level, we found high ITH of druggable gene EGFR and FGFR1 in approximately 50% FGFR1- and EGFR-amplified cases, indicating that the mutation status of these two targets from single-tumor sequencing may underestimate their ITH." (PMID 30975989, 2019). "Thus, combined treatment with PTX and BGJ398 not only induces tumor cell apoptosis but may also block metastatic progression by suppressing FGFR1-mediated migration and colony formation of mesenchymal-type UC cells." (PMID 30326563, 2018). "The data presented here suggests that while Vegfr2 heterozygosity strikingly leads to defects in tumor growth and tumor angiogenesis in all the three tumor models, additional loss of endothelial Fgfr1 and Fgfr2 displays no further effects on tumor growth and tumor angiogenesis." (PMID 30283071, 2018). "After correction for age, tumor size, stage and grade, ER/PR/HER2 status and 3-gene classifier subtype, the loss of WRN (p=0.053; HR 1.2), DUSP26 (p=0.022; HR 1.3), UNC5D (p=0.026; HR 1.3), ZNF703 (p=0.026; HR 1.3) and FGFR1 (p=0.002; HR 1.5) still predicted worse DFS." (PMID 29682206, 2018). "FGFR1 amplification induced a strong FGFR1 dependency that could be exploited therapeutically, and in vivo studies have demonstrated inhibition of the FGFR1 pathway with FGFR inhibitors that led to significant tumor shrinkage, and translational clinical trials are undertaken." (PMID 29088806, 2017). "In the xenograft model of H1581 cells, we confirmed that the FGFR1 inhibitor AZD4547 could repress the growth of tumor inoculated either from the oncospheres or parental cells; the inhibitor could also reduce the ALDH positive proportion of tumors in both these two models." (PMID 26936993, 2016).
tumor (continued). "K19 may enhance tumour angiogenesis by regulating FGFR1, VASH1, and VASH2 in HCC." (PMID 27863477, 2016). "However, we identified correlations between ESRPs and FGFR1-3 IIIb/IIIc splice variants in non-neoplastic colorectal epithelium but not in the matched adjacent tumor." (PMID 27650542, 2016). "Furthermore, there was a significant positive correlation between the expression of FGFR1-FGFR2 (ρ = 0.24, p = 0.026) and FGFR2-FGFR3 (ρ = 0.23, p = 0.031) in tumor tissues, while FGFR1 expression was inversely correlated with FGFR3 expression (ρ = −0.30, p = 0.005)." (PMID 27669755, 2016). "In addition, we also detected FGFR1 protein expression in tumor tissues from nude mice models." (PMID 25760077, 2015). "Interestingly, FGFR1 expression was increased in both noninvasive and invasive tumours." (PMID 22899908, 2012). "Of note, the two models in which the primary tumor clustered closest to allografts (ALK- and FGFR1-driven) had been cultured for eight and nine passages, respectively, whereas NTRK-driven tumor cells were only in culture for six passages." (PMID 41381884, 2026). "In xenograft models, msFGFR2-IIIc significantly suppressed tumor growth, suggesting its utility in cancers co-expressing FGFR2-IIIc and FGFR1-IIIc isoforms." (PMID 41584352, 2026). "In this study, we demonstrate that erdafitinib effectively suppresses tumor growth in JMSU1 cells, a model of FGFR1-amplified MIBC." (PMID 41315241, 2025). "Experiments such as using CRISPR-Cas9 system to knockout FGFR1 gene in DU145 to generate a new experiment system—FGFR1 null DU145 cells are needed to confirm the link between FGFR1 and LDHA with tumor cell phenotype." (PMID 40995571, 2025). "In contrast, acquired resistance mechanisms include the activation of compensatory pathways such as FGFR1, MAPK, PI3K/AKT/mTOR, Myc, Hippo, tumor metabolism, and alterations in the TME." (PMID 39955556, 2025). "Nintedanib inhibition of FGFR1, along with VEGFR and PDGFR, results in suppression of angiogenesis, fibroblast proliferation, and tumor growth." (PMID 41226200, 2025). "Ferulic acid inhibits angiogenesis by targeting the fibroblast growth factor receptor 1 (FGFR1) and blocking the PI3K-Akt signaling pathway, which is critical for tumor growth and vascularization." (PMID 40325268, 2025). "Targeting FGFR1 with monoclonal antibodies and tyrosine kinase inhibitors has emerged as a promising therapeutic strategy to enhance ICI efficacy by altering the tumor microenvironment and countering immune suppression." (PMID 40547805, 2025). "This orally administered multi-targeted tyrosine kinase inhibitor exerts its anti-tumor effects by inhibiting the tyrosine kinase activity of FGFR1-4, thereby blocking FGFR signaling and suppressing tumor cell proliferation." (PMID 41438986, 2025). "Deacetylated KLF5 also upregulated CX3CR1 expression in tumor cells, further amplifying FGF9-driven FGFR1 activation." (PMID 41514658, 2025). "We found that in both metabolism-related pathways, SLC5A3 + tumor cells exhibit significant communication with CAFs, particularly through the FN1/SDC2, FGF7/FGFR1, NGF/SORT1, and LRPAP1/LRP1 receptor-ligand pairs." (PMID 40652057, 2025). "Because FGFR1 activation leads to MAPK signaling, IHC with phospho p44/42 MAPK was performed on this tumor, which showed diffuse signals in tumor cells, consistent with MAPK activation." (PMID 41323387, 2025). "Collectively, aberrant alternative splicing of FGFR1–3 adds an additional layer of complexity to FGFR dysregulation in solid tumors, with implications for tumor biology, biomarker interpretation, and therapeutic targeting." (PMID 41514604, 2025). "The expression of FGFR‐1 activated by VEGF‐A for angiogenesis was also suppressed by both PX‐478 and BPR0C261 in extracts of MTCQ‐1 tumours." (PMID 39757131, 2025). "VEGF receptors (KDR, FLT4, FGFR1, and FLT3) and FGF receptors support tumor angiogenesis, providing essential nutrients for growth." (PMID 39273340, 2024).
tumor (continued). "Tumor sequencing revealed LOH in CHEK2 and PALB2, as well as CCND1,FGFR1, GPR124, ZNF217, ZNF703, and PTPN1 amplifications." (PMID 38091153, 2024). "Most of anlotinib’s targets were upregulated in DDLPS, while FGFR1, PDGFRA and PDGFRB were significantly upregulated in tumor tissues." (PMID 39117615, 2024). "Considering that IP injection of the FGFR1 inhibitor PD173074 at 1 mg/kg/day has been utilized to inhibit FGFs-induced angiogenesis and at 20–50 mg/kg/day to elucidate the anti-tumor effect of FGFs, 2 mg/kg/day was administered in our study." (PMID 38673797, 2024). "N-cadherin interacts with fibroblast growth factor receptor 1, leading to the continuous activation of the MAPK-ERK pathway and the promotion of tumor cell survival via stromal interaction." (PMID 39519372, 2024). "Dysregulation of FGFR expression can contribute to tumor cell proliferation, survival, resistance, and immune escape, with LSCC showing higher FGFR1 levels than LUAD." (PMID 39544292, 2024). "Analysis of the TCGA database in TNBC samples revealed a correlation between the mRNA expression of FGFR1, FGFR2, and FGF2 and the hypomethylation status of tumour cells." (PMID 40135140, 2024). "A novel FGFR1 inhibitor, CYY292, showed promising results in inhibiting tumor growth by inhibiting the Akt/GSK3β/snail signaling axis in glioblastoma; Pemigatinib was also found to induce a partial response along with neurological improvement." (PMID 39796710, 2024). "IHC experiments displayed that the positive expressions of Ki67(a well-known marker of cell proliferation), OTUD4, CDK1, FGFR1 and p-BRAF were obviously decreased in tumor xenografts with OTUD4 knockdown." (PMID 38429268, 2024). "Gremlin1 promotes tumor cell proliferation and resistance to androgen deprivation therapy (ADT) by binding to fibroblast growth factor receptor 1 (FGFR1) and activating downstream mitogen-activated protein kinase (MAPK) signaling pathways." (PMID 39590377, 2024). "PD173074 is a potent inhibitor of FGFR1 and VEGFR2, showing inhibitory effects on TNBC in both in vitro and in vivo assays, as well as anti-tumour activity in FGFR-amplified TNBC cell lines." (PMID 40135140, 2024). "This fusion leads to the constitutive activation of FGFR1; BCR-FGFR1 activates the ERK/MAPK and JAK/STAT pathways and exhibits transformative activity in NIH3T3 cells, promoting tumor development." (PMID 39590377, 2024). "Basic FGF (bFGF, FGF2) is an important ligand of FGFR1 in GBM, and together, they increase self-renewal and maintenance of GBM cancer stem cells, thereby driving tumor growth." (PMID 39682716, 2024). "Surufatinib, a novel small-molecule inhibitor, exhibits a unique dual action by targeting both tumor angiogenesis (VEGFR1/2/3 and FGFR1) and immune evasion through the macrophage colony-stimulating factor 1 (CSF1) receptor." (PMID 38730642, 2024). "We detected expression of FGFR1 and FGFR2 in tumor organoids, with higher levels in embryonal than fetal organoids, while FGFR4 was exclusively expressed in fetal tumor organoids." (PMID 39567475, 2024). "Lenvatinib prevents tumor angiogenesis through inhibition of VEGFR-1, -2, and -3, and also blocks the proliferation of tumor cells through inhibition of FGFR-1, FGFR-2, FGFR-3, & FGFR-4, PDGFRα, RET, and c-KIT." (PMID 38622735, 2024). "While TCM from untreated BC cells induced increased expression of VEGFR2, VEGFA, FGFR1, HIF-1α and PDGFRB, this effect was significantly inhibited by the muscone administration to tumor cells prior to isolation of the 231TCM and 549TCM." (PMID 38898449, 2024). "This is supported by scRNA-seq data showing the expression of FGFR1 and various FGF ligands (e.g., FGF3, 8, 9, 19) in tumor tissues and organoids." (PMID 39567475, 2024). "Cell viability of U251 cells overexpressing FGFR1-EGFP was strongly increased by SPRY2-OE even after cisplatin treatment, which confirms our previous study that SPRY2-OE increases tumor growth of U251 xenografts in mice." (PMID 39682716, 2024).
tumor (continued). "Among the FGFR family members (FGFR1, FGFR2, FGFR3, and FGFR4), only FGFR2 was significantly upregulated in PanCK(+) tumor epithelial cells at the EOCC tumor invasive margin compared to the LOCC tumor invasive margin in NGDSP analysis." (PMID 37964075, 2023). "PDGFR-α, PDGFR-β, c-Kit, FGFR1, and anaplastic lymphoma receptor tyrosine kinase (ALK) were overexpressed in the tumour tissues compared with their levels in normal tissues." (PMID 38332765, 2023). "FGFR1 is the most widely reported and studied gene among the FGFR family members, and it has been widely reported as an oncogene to promote tumor initiation and development, indicating its importance in tumorigenesis." (PMID 37750089, 2023). "Mechanistically, we unveil that VEGF-B binds to FGFR1, induces FGFR1/VEGFR1 complex formation, and suppresses FGF2-induced Erk activation, and inhibits FGF2-driven angiogenesis and tumor growth." (PMID 37591843, 2023). "Another study showed that either Fgfr1, Fgfr2, or Fgfr3 gene knockout impeded SS18-SSX2-induced tumour formation in vivo and FGFR inhibitor (BGJ398) treatment reduced SS tumour cell growth in vitro and in vivo." (PMID 37130917, 2023). "Mechanistically, we discovered that VEGF-B binds to FGFR1, induces FGFR1/VEGFR1 complex formation, inhibits FGF2-induced Erk activation, and thereby suppresses FGF2-driven angiogenesis and tumor growth." (PMID 37591843, 2023). "After validating anti-FGFR antibodies, we determined expression of FGFR1 in orthotopic patient-derived xenograft models of GBM, comparing central areas of the tumor core to the invasive edge." (PMID 37579831, 2023). "In summary, our study demonstrates differential expression of FGFR1 and FGFR2 on invasive GBM cells and provides functional and transcriptomic evidence that FGFR1 regulates tumor invasion in GBM." (PMID 37579831, 2023). "The probability of interaction between tumor cells and fibroblast receptor-ligand pairs was higher than that of thyroid cells, especially in TGFB1/ACVR1/TGFBR1, FGF18/FGFR1, BTC/EGFR, BMP8A/BMPR1A/BMPR2, and BMP8A/BMPR1A/BMPR2." (PMID 37733241, 2023). "We quantify relative expression levels of FGFR1 and FGFR2 in GBM patient-derived xenograft models and compare expression within the tumor core and the invasion front." (PMID 37579831, 2023). "FGFR1 was amplified in a PDX bone metastasis model of PDAC, which showed reduced tumour growth and bone metastases following treatment with AZD4547." (PMID 36357571, 2023). "CSF1R, FGFR1, FLT3, and KDR are related to the tumor microenvironment, and ERBB4, STK11, PTEN, and NPM1 are related to proliferation-related factors." (PMID 36780540, 2023). "Additionally, the downregulated levels of miR-296 are notably related to a worrisome prognosis in HCC, while the enhancement of its expression levels could limit tumor growth, induce apoptosis, and regulates the cell cycle via interacting with the fibroblast growth factor receptor 1 (FGFR1) gene." (PMID 37108330, 2023). "The increased level of FGF2 in tumor microenvironment promotes TAM polarization and infiltration through FGFR1/PI3K/AKT axis, thereby resulting in poor prognosis of GC patients." (PMID 36681667, 2023). "Sorafenib has tumor-agnostic efficacy in patients with tumors harboring genomic alterations in PDGFRA/B, VEGF-Rs, Flt-3, KIT, FGFR1 or the RAF/MEK/ERK pathway." (PMID 37444551, 2023). "As tumour cells showed PDGFR-α, c-Kit, and FGFR1 overexpression, the anticancer effect of tyrosine kinase inhibitors was evaluated on the cells; toceranib was the most effective and was administered starting with an extra-labelled dose." (PMID 38332765, 2023). "To further validate differences in FGFR1 and FGFR2 expression within GBM, we identified publicly available RNA-seq datasets that compared tumor core versus infiltrating regions." (PMID 37579831, 2023).